LUM (lumican)
Synonyms: LDC; SLRR2D
Tractability: Antibody: its Gene Ontology location is reachable by antibodies, with high confidence; UniProt places it where antibodies can reach, with medium confidence; UniProt predicts a signal peptide or a membrane-spanning region.
Gene: Protein-coding gene on chromosome 12 (91,102,629 to 91,111,512, reverse strand). Ensembl gene ENSG00000139329.
Subcellular location: Secreted, extracellular space, extracellular matrix
Pathways (Reactome):
Disease: Defective B4GALT1 causes B4GALT1-CDG (CDG-2d); Defective CHST6 causes MCDC1; Defective ST3GAL3 causes MCT12 and EIEE15
Extracellular matrix organization: ECM proteoglycans; Integrin cell surface interactions
Metabolism: Keratan sulfate biosynthesis; Keratan sulfate degradation
Gene Ontology:
Molecular function: collagen binding; protein binding; extracellular matrix structural constituent; extracellular matrix structural constituent conferring compression resistance
Biological process: collagen fibril organization; visual perception; cartilage development; positive regulation of transforming growth factor beta1 production; response to Aroclor 1254; response to growth factor
Cellular component: extracellular exosome; extracellular matrix; extracellular region; fibrillar collagen trimer; gel phase of interstitial matrix; Golgi lumen; lysosomal lumen
Genetic constraint (gnomAD): Loss-of-function variants: 12 observed, 19.01 expected, observed/expected ratio (o/e) 0.63, 90% interval 0.4 to 1.02. The upper end of that interval is the gene's LOEUF score, 1.02, which puts it in group 4 of 6, group 1 being the genes least tolerant of losing a copy. Missense variants: 295 observed, 380.75 expected, observed/expected ratio (o/e) 0.77, 90% interval 0.7 to 0.85. Synonymous variants: 159 observed, 149.9 expected, observed/expected ratio (o/e) 1.06, 90% interval 0.93 to 1.21.
Homologues: Orthologues: chimpanzee LUM (99% identical), macaque LUM (98% identical), dog LUM (91% identical), rabbit LUM (91% identical), pig LUM (89% identical), mouse Lum (87% identical), rat Lum (85% identical), guinea pig LUM (84% identical), tropical clawed frog lum (64% identical), zebrafish lum (49% identical). Paralogues in human: FMOD (45% identical), OMD (40% identical), PRELP (40% identical), KERA (36% identical), ECM2 (33% identical), LINGO4 (24% identical), LINGO3 (21% identical), OGN (21% identical), EPYC (19% identical), OMG (18% identical).
Diseases named in the same sentence as LUM in open-access papers:
LUM is named in the same sentence as 185 diseases in open-access papers, as found by Europe PMC text mining. Sharing a sentence is not in itself a finding about the gene and the disease. The quoted sentences say what the papers report.
melanoma (40 papers, 2008 to 2025). A malignant, usually aggressive tumor composed of atypical, neoplastic melanocytes. "Our data clearly indicate that lumican deficiency is associated with fast-growing melanoma allografts that display increased biochemical heterogeneity, as revealed using unsupervised K-means classification of tumor tissue FT-IR absorbance spectra." (PMID 28794454, 2017). "This should be put in perspective with previous work underlying decreased lumican expression within the most infiltrative melanoma lesions." (PMID 28794454, 2017). "Moreover, LUM upregulation has been demonstrated in some cancers such as breast carcinoma, related to increased levels of metastasis, melanoma and in cancer associated fibroblasts (CAFs) of esophageal squamous cell carcinoma (ESCC)." (PMID 38322285, 2023). "While lumican overexpression has been associated with poor prognosis in some malignancies, such as breast and pancreatic cancers, its tissue level was found to be increased in osteosarcoma and melanoma patients with better survival." (PMID 35454809, 2022). "Similarly, the downregulation of lumican expression in melanoma was associated with increased invasion." (PMID 34885059, 2021). "Therefore, in addition to inducing the apoptosis of melanoma cells, lumican inhibited tumor-associated angiogenesis." (PMID 34572532, 2021). "Co-expression analyses were first performed among TCGA melanoma dataset, highlighting that human LUM mRNA levels correlate with expression of genes encoding for α chains of type I and type III collagens, i.e. two of the most abundant matrix components within a tumor microenvironment." (PMID 28794454, 2017). "In addition, the altered expression of lumican and decorin has been associated with various human cancers including breast, pancreatic, lung, ovarian, melanoma, colorectal, osteosarcoma and ductal adenocarcinoma." (PMID 20540791, 2010). "Lumican has been shown to reduce MMP-releasing invadopodia to inhibit melanoma lung metastasis in vivo and to decrease the expression of MMPs to inhibit breast cancer migration and invasion." (PMID 39334952, 2024). "LUM inhibits snail-induced melanoma migration by blocking MMP-14 activity, inhibits B16F1 melanoma cell lung metastasis and also inhibits prostate cancer development." (PMID 38474072, 2024). "Conversely, overexpression of PIR mRNA was associated with weaker LUM and THY-1 gene expression in transfected melanoma cells relative to the control cells." (PMID 37308689, 2023). "In bladder cancer, GBM and melanoma, relations between LUM and prognosis and the relation between LUM and CTL were inconsistent." (PMID 37692065, 2023). "In melanoma, elevated LUM levels inhibit cancer cell proliferations by suppressing MMP-14 activities or inhibiting focal adhesion kinase phosphorylation." (PMID 37692065, 2023). "Confirmation of the anti-cancer properties of lumican came from studies demonstrating the capacity of proteoglycan to inhibit in vitro colony formation of melanoma cells transformed by oncogenes H-ras, v-K-ras, and v-src." (PMID 35454809, 2022). "In melanoma, LUM in the extracellular matrix halts metastasis through direct interaction with alpha-2-beta-1 integrin." (PMID 36873459, 2022). "Lumican was shown to inhibit the development of the melanoma primary tumor as well as lung metastatic nodules development." (PMID 33917849, 2021). "Recently, in a mouse model of primary melanoma, the lumican-derived L9Mc peptide abrogated the growth and increased the apoptosis of B16F1 cells, as determined by infrared spectral imaging and histopathology." (PMID 34572532, 2021). "On the other hand, in Snail-B16F1 melanoma cells treated with lumican, vinculin expression is reduced." (PMID 33917849, 2021). "In this model, endogenous lumican was demonstrated to inhibit the primary melanoma tumor development, while Snail overexpression was shown to induce EMT and the metastatic potential of melanoma cells." (PMID 33917849, 2021).
melanoma (continued). "In melanoma and breast cancer, lumican exerts anticancer properties, and lumican-based therapeutic strategies have been examined." (PMID 34572532, 2021). "Previous studies have shown the ability of lumican (and its derived peptides), in contrast to decorin (DCN), to inhibit MMP-14 activity in melanoma cells, where lumican directly interacted with MMP-14." (PMID 34885059, 2021). "Cell invasion is a crucial biological property, and therefore the effect of lumican on melanoma cell invasion properties was analyzed by an in vitro cell invasion assay." (PMID 33917849, 2021). "In the presence of lumican, the number of cells migrating through the pre-coated inserts was significantly decreased for both melanoma Mock- and Snail-B16F1 cells." (PMID 33917849, 2021). "Lumican has an anti-tumor effect in breast cancer, pancreatic cancer, and malignant melanoma by counteracting MMP-14 signaling, among other things." (PMID 35008569, 2021). "Second harmonic generation (SHG) and Fourier transform infrared (FTIR) imaging techniques were used to evidence ECM disorganization by lumican in melanoma and, more specifically, collagen fiber orientation." (PMID 34885059, 2021). "It has been shown that lumican delays melanoma growth in mice and plays regulatory roles in functional properties and invadopodia formation in breast cancer cells." (PMID 33917849, 2021). "In Snail overexpressing Snail-B16F1 cells, lumican significantly inhibits and melanoma primary tumor development." (PMID 34572532, 2021). "On the other hand, the lumican expression is suggested to attenuate discrete tumor progression, including pancreatic cancerand melanoma, as recently discussed." (PMID 34572532, 2021). "In vivo experiments in lumican-null mice revealed that lumican is an endogenous inhibitor of melanoma growth and modulates the response to TAX2, an anticancer cyclic peptide." (PMID 34572532, 2021). "The effect of lumican on melanoma lung metastasis in wild type and lumican-deleted mice was investigated after 14 days." (PMID 33917849, 2021). "Lumican was shown to inhibit melanoma cell migration, while promoting their adhesion, notably by direct interaction with α2β1 integrin." (PMID 34885059, 2021). "Several experiments have shown that an increase of lumican expression in melanoma will reduce its growth and invasion." (PMID 33493133, 2021). "The results show that endogenous lumican inhibits the cell proliferation in lung metastatic nodules of melanoma cells." (PMID 33917849, 2021). "SEM was performed to investigate the potential lumican regulatory effect on melanoma cells (Mock-B16F1 and Snail-B16F1) showing morphological characteristics related to cancer cell aggressiveness." (PMID 33917849, 2021). "Previous studies from our laboratories showed that MMP-14 activity was inhibited by lumican in melanoma." (PMID 33917849, 2021). "In this report, our aim was to assess by FTIR imaging the effect of antitumoral effectors, such as the L9Mc lumican-derived peptide on primary melanoma development." (PMID 32548117, 2020). "Lumican overexpression decreases subcutaneous primary melanoma tumor growth in vivo, with a concomitant decrease of cyclin D1 expression as well as a decrease in the number of lung metastatic nodules in which an increase of tumor cell apoptosis was observed." (PMID 32548117, 2020). "The majority of these studies showed that the expression of lumican was abnormal; the cancer types studied included gastric cancer, colorectal cancer, pancreatic cancer, breast cancer, malignant melanoma, and other malignant tumor tissues." (PMID 32500021, 2020). "Lumcorin, a lumican-derived peptide mimics the inhibitory effect of lumican in melanoma progression." (PMID 32351878, 2020). "Potentiation of MMP-14 activity by Snail was previously observed by us in B16F1 melanoma cells, and this effect was inhibited by Lumican (LUM)." (PMID 32629890, 2020).
melanoma (continued). "Lumican, an antiproliferative PG, inhibited cell growth potential in melanoma cells and inhibited cell proliferation in animal models of melanoma and pancreatic cancer." (PMID 32825245, 2020). "In the present report, we conducted an investigation combining IR spectral histopathology (IRSH), conventional histology and immunohistochemistry to study the effect of lumican-derived peptide (L9Mc) on tumor progression in melanoma primary tumors." (PMID 32548117, 2020). "From a therapeutic point of view, for example in the context of tumor progression such as melanoma, it will be important to study the drug delivery potential taking into account the role of lumican in ECM integrity." (PMID 32478070, 2020). "Lumican derived peptides–lumcorin, have been tested against melanoma and show therapeutic potential by inhibiting cell chemotaxis and melanoma growth through MMP-14 inhibition." (PMID 32082161, 2019). "Lumican was previously reported as being expressed within tumor stroma of malignant melanoma, while inversely correlating with malignancy according to Clark levels that reflect disease vertical progression." (PMID 28794454, 2017). "In this report, a comprehensive review of available public clinical data for melanoma is first provided, highlighting a correlation between lumican expression and patient outcome." (PMID 28794454, 2017). "A comprehensive and large-scale mining of public microarray databases was first performed in this study, thus unambiguously demonstrating a correlation between altered lumican expression and poor outcome in human melanoma." (PMID 28794454, 2017). "Earlier in vivo work using B16F1 cells engineered to express lumican strongly suggested its involvement in the control of melanoma progression." (PMID 28794454, 2017). "Using KO mice, we then extensively studied the role of host lumican on tumor ECM organization as well as on disease progression using an immunocompetent model of B16F1 melanoma allograft." (PMID 28794454, 2017). "Altogether, this first round of data arising from multiple databases analyses undoubtedly establishes a relationship between altered lumican expression and poor clinical outcome in human melanoma." (PMID 28794454, 2017). "IHC analysis of lumican reveals a strong staining in the dermis and especially at the stromal margin surrounding melanoma allografts implanted in WT mice." (PMID 28794454, 2017). "Here, we investigate the role of host lumican on tumor matrix organization as well as on disease progression considering an immunocompetent model of melanoma implanted in Lum−/−vs. wild type syngeneic mice." (PMID 28794454, 2017). "A thorough screening of multiple melanoma clinical datasets further highlighted that both alterations in LUM gene sequence as well as lower mRNA expression are associated with decreased patient survival." (PMID 28794454, 2017). "Using knockout mice (Lum−/−), the present report demonstrates for the first time that lumican is an endogenous inhibitor of melanoma tumor growth." (PMID 28794454, 2017). "Then, B16 melanoma allografts were transplanted in both WT and Lum KO mice in order to characterize the influence of host lumican on tumorigenesis." (PMID 28794454, 2017). "Contrary to what is observed regarding collagen-encoding genes, our present bioinformatics studies further revealed that MMP14 inversely correlates with LUM expression in melanoma, with decreased survival being related to higher MMP14 expression." (PMID 28794454, 2017). "In the B16 melanoma allograft model, endogenous lumican inhibits tumor growth and modulates response to TAX2 peptide." (PMID 28794454, 2017). "Data from our laboratory demonstrated anti-tumorigenic properties of lumican in melanoma both in vitro and in vivo." (PMID 26930497, 2016). "Lumican inhibits melanoma cell migration by alteration of the actin network and focal adhesion complexes and this process is mediated by α2β1 integrin that binds lumican directly." (PMID 26930497, 2016).
melanoma (continued). "The expression of lumican is preferentially located at the periphery of the melanoma tumor in stromal dermal fibroblasts." (PMID 26930497, 2016). "We recently showed that the glycosylated form of lumican was able to significantly decrease MMP-14 activity in B16F1 melanoma cells." (PMID 26930497, 2016). "As reported, lumican promotes neutrophil migration by interaction with integrin β2, while it inhibits melanoma cell migration through integrin α2β1." (PMID 23840601, 2013). "It was shown that melanoma cells, when in contact with a lumican core protein substratum, exhibited a change in the distribution of the β1 integrin subunit on cell membrane." (PMID 24098450, 2013). "In vitro, it was demonstrated that the inhibition of melanoma cell chemotactic migration by lumican is due to a specific sequence of the core protein located in the LRR9 domain." (PMID 24098450, 2013). "In this study, we characterized some properties of lumican – derived peptides on anchorage dependent and independent growth and spontaneous migratory properties of melanoma cells." (PMID 24098450, 2013). "Lumican is able to significantly inhibit the anchorage-independent growth of melanoma cells in soft agar." (PMID 24098450, 2013). "Previous works from our group showed that lumican inhibited melanoma cell migration and tumor growth in vitro and in vivo." (PMID 24098450, 2013). "Melanoma cells adhered to lumican, resulting in a remodeling of their actin cytoskeleton and preventing their migration." (PMID 24098450, 2013). "Lumcorin, similarly to lumican, acts on two fundamental processes connected to melanoma progression: cell growth and migration." (PMID 24098450, 2013). "The inhibition of melanoma cell migration by lumican was correlated with the inhibition of the phosphorylation of focal adhesion kinase (FAK)." (PMID 24098450, 2013). "Previous studies had revealed that lumican can interact with integrin α2 in endothelial cells and melanoma cells." (PMID 23840601, 2013). "Lumican was shown to inhibit melanoma progression in vivo with a concomitant decrease of cyclin D1 expression and to induce and/or increase apoptosis." (PMID 24098450, 2013). "Lumican was able to inhibit melanoma cell migration via alteration of the actin network and focal adhesion complexes." (PMID 23236386, 2012). "LUM, whose expression is down regulated in most metastatic melanomas, is another member of the family of small proteoglycans that includes decorin for which an anti-invasive role was reported." (PMID 18211678, 2008). "Many of these downregulated proteomic cargoes in melanoma sEVs, including collagens (COL1A1, COL3A1, COL6A1–A3, and COL14A1), matrix-associated proteoglycans (DCN, LUM, FMOD, OGN, and PRELP), and structural regulators (TNXB and PCOLCE), are key components of ECM organization and tensile strength." (PMID 41271007, 2025). "LUM peptides inhibit melanoma spread and suppress pancreatic cancer." (PMID 38474072, 2024). "However, in the GSE78220 cohort with melanoma, we found that high LUM expression was more likely to be unresponsive to immunotherapy, which is consistent with TMB and MSI predictions." (PMID 37692065, 2023). "Low expression levels of LUM at the tumor margin in malignant melanoma may promote the proliferation of melanoma cells; however, whether LUM acts as a tumor suppressor or oncogenic gene depends on the cellular environment and thus related to the TME." (PMID 36686480, 2022). "Therefore, the aim of this study was to examine the effect of lumican on Mock and Snail overexpressing melanoma B16F1 cells in vivo." (PMID 33917849, 2021). "In contrast, Snail-B16F1 melanoma cells cultured for 24 h in presence of lumican appeared as grouped cells exhibiting cell–cell tight contacts and few microvesicles on their surface, while others appeared almost completely smooth with no microvesicles or microvilli." (PMID 33917849, 2021).